NOD2 (nucleotide binding oligomerization domain containing 2)
Description:
Pattern recognition receptor (PRR) that detects bacterial peptidoglycan fragments and other danger signals and plays an important role in gastrointestinal immunity. Specifically activated by muramyl dipeptide (MDP), a fragment of bacterial peptidoglycan found in every bacterial peptidoglycan type. NOD2 specifically recognizes and binds 6-O-phospho-MDP, the phosphorylated form of MDP, which is generated by NAGK. 6-O-phospho-MDP-binding triggers oligomerization that facilitates the binding and subsequent activation of the proximal adapter receptor-interacting RIPK2. Following recruitment, RIPK2 undergoes 'Met-1'- (linear) and 'Lys-63'-linked polyubiquitination by E3 ubiquitin-protein ligases XIAP, BIRC2, BIRC3 and the LUBAC complex, becoming a scaffolding protein for downstream effectors, triggering activation of the NF-kappa-B and MAP kinases signaling. This in turn leads to the transcriptional activation of hundreds of genes involved in immune response. Its ability to detect bacterial MDP plays a central role in maintaining the equilibrium between intestinal microbiota and host immune responses to control inflammation (By similarity). An imbalance in this relationship results in dysbiosis, whereby pathogenic bacteria prevail on commensals, causing damage in the intestinal epithelial barrier as well as allowing bacterial invasion and inflammation (By similarity). Acts as a regulator of appetite by sensing MDP in a subset of brain neurons: microbiota-derived MDP reach the brain, where they bind and activate NOD2 in inhibitory hypothalamic neurons, decreasing neuronal activity, thereby regulating satiety and body temperature (By similarity). NOD2-dependent MDP-sensing of bacterial cell walls in the intestinal epithelial compartment contributes to sustained postnatal growth upon undernutrition (By similarity). Also plays a role in antiviral response by acting as a sensor of single-stranded RNA (ssRNA) from viruses: upon ssRNA-binding, interacts with MAVS, leading to activation of interferon regulatory factor-3/IRF3 and expression of type I interferon. Also acts as a regulator of autophagy in dendritic cells via its interaction with ATG16L1, possibly by recruiting ATG16L1 at the site of bacterial entry. NOD2 activation in the small intestine crypt also contributes to intestinal stem cells survival and function: acts by promoting mitophagy via its association with ATG16L1 (By similarity). In addition to its main role in innate immunity, also regulates the adaptive immune system by acting as regulator of helper T-cell and regulatory T-cells (Tregs) (By similarity). Besides recognizing pathogens, also involved in the endoplasmic reticulum stress response: acts by sensing and binding to the cytosolic metabolite sphingosine-1-phosphate generated in response to endoplasmic reticulum stress, initiating an inflammation process that leads to activation of the NF-kappa-B and MAP kinases signaling. May also be involved in NLRP1 activation following activation by MDP, leading to CASP1 activation and IL1B release in macrophages. [Isoform 2]: Acts as a pattern recognition receptor (PRR); able to activate NF-kappa-B. [Isoform 3]: Can activate NF-kappa-B in a muramyl dipeptide (MDP)-independent manner.
Synonyms: CARD15; BLAU; CD; PSORAS1; CLR16.3; NLRC2; ACUG; BLAUS; IBD1; NOD2B; YAOS
Tractability: Small molecule: an approved drug acts on it; a high-quality ligand is known; it belongs to a druggable protein family. Antibody: UniProt places it where antibodies can reach, with high confidence; its Gene Ontology location is reachable by antibodies, with high confidence. PROTAC: UniProt records ubiquitination sites on it; ubiquitination databases record sites on it; a small molecule that binds it is known.
Gene: Protein-coding gene on chromosome 16 (50,693,217 to 50,733,348, forward strand). Ensembl gene ENSG00000167207.
Subcellular location: Cell membrane; Basolateral cell membrane; Cytoplasm; Mitochondrion; Cytoplasm (Isoform 3)
Subcellular location (Human Protein Atlas): Cytosol; Golgi apparatus
Pathways (Reactome):
Immune System: Interleukin-1 signaling; JNK (c-Jun kinases) phosphorylation and activation mediated by activated human TAK1; NOD1/2 Signaling Pathway; TAK1-dependent IKK and NF-kappa-B activation; activated TAK1 mediates p38 MAPK activation
Disease: SARS-CoV-2 activates/modulates innate and adaptive immune responses
Metabolism of proteins: Ovarian tumor domain proteases
Gene Ontology:
Molecular function: actin binding; CARD domain binding; enzyme binding; Hsp70 protein binding; Hsp90 protein binding; muramyl dipeptide binding; pattern recognition receptor activity; peptidoglycan binding; protein binding; protein kinase binding; protein-containing complex binding; ubiquitin binding; ADP binding; anion binding; carbohydrate derivative binding
Biological process: antibacterial innate immune response; canonical NF-kappaB signal transduction; cellular response to lipopolysaccharide; cellular response to muramyl dipeptide; defense response to bacterium; detection of bacterium; detection of muramyl dipeptide; innate immune response; intracellular signal transduction; maintenance of gastrointestinal epithelium; nucleotide-binding oligomerization domain containing 2 signaling pathway; pattern recognition receptor signaling pathway; positive regulation of B cell activation; positive regulation of canonical NF-kappaB signal transduction; positive regulation of cytokine production involved in immune response; positive regulation of cytokine production involved in inflammatory response; positive regulation of interleukin-1 beta production; positive regulation of interleukin-17 production; positive regulation of interleukin-6 production; positive regulation of interleukin-8 production; positive regulation of JNK cascade; positive regulation of non-canonical NF-kappaB signal transduction; positive regulation of protein K63-linked ubiquitination; positive regulation of stress-activated MAPK cascade; positive regulation of transcription by RNA polymerase II; and 24 more
Cellular component: basolateral plasma membrane; cell surface; cytoplasm; cytoskeleton; cytosol; extrinsic component of plasma membrane; mitochondrion; phagocytic vesicle; plasma membrane; protein-containing complex; vesicle
Genetic constraint (gnomAD): Loss-of-function variants: 76 observed, 89.06 expected, observed/expected ratio (o/e) 0.85, 90% interval 0.71 to 1.03. The upper end of that interval is the gene's LOEUF score, 1.03, which puts it in group 4 of 6, group 1 being the genes least tolerant of losing a copy. Missense variants: 1,214 observed, 1,305.9 expected, observed/expected ratio (o/e) 0.93, 90% interval 0.89 to 0.98. Synonymous variants: 561 observed, 566.42 expected, observed/expected ratio (o/e) 0.99, 90% interval 0.92 to 1.06.
Gene-disease validity (ClinGen):
ClinGen rates the evidence that NOD2 causes each of these diseases.
Blau syndrome (autosomal dominant): Definitive. Blau syndrome (BS) is a rare systemic inflammatory disease characterized by early onset granulomatous arthritis, uveitis and skin rash.
Homologues: Orthologues: chimpanzee NOD2 (99% identical), macaque NOD2 (96% identical), rabbit NOD2 (86% identical), dog NOD2 (83% identical), pig NOD2 (82% identical), guinea pig NOD2 (82% identical), rat Nod2 (80% identical), mouse Nod2 (79% identical), zebrafish nod2 (46% identical). Paralogues in human: NOD1 (31% identical), NLRC3 (21% identical), NLRC5 (20% identical), NLRP3 (20% identical), NLRP12 (19% identical), NLRP2 (18% identical), NLRP4 (17% identical), NLRP1 (17% identical), NLRP7 (17% identical), CIITA (17% identical), NLRP9 (17% identical), NLRP14 (16% identical), and 8 more.
Diseases named in the same sentence as NOD2 in open-access papers:
NOD2 is named in the same sentence as 407 diseases in open-access papers, as found by Europe PMC text mining. Sharing a sentence is not in itself a finding about the gene and the disease. The quoted sentences say what the papers report.
Crohn disease (421 papers, 2005 to 2026). A gastrointestinal disorder characterized by chronic inflammation involving all layers of the intestinal wall, noncaseating granulomas affecting the intestinal wall and regional lymph nodes, and transmural fibrosis. "NOD2 variants that impair signaling ability are associated with Crohn’s disease, leading to dysbiosis in the gastrointestinal tract." (PMID 40613780, 2025). "For instance, certain gene mutations in inflammatory bowel disease, such as those in the NOD2/CARD15 gene, have been associated with Crohn’s disease." (PMID 40003627, 2025). "Other examples are Crohn’s disease (40%) and Yao syndrome which are associated frequently with NOD2 variants of low penetrance but with larger effects than standard genome-wide association study (GWAS) signals." (PMID 40282361, 2025). "First, it relied on a robust sample size of 310 individuals, including 250 well-characterized adult patients with IBD, with genotype status specifically assessed for the three main disease-associated NOD2 variants in patients with Crohn’s disease." (PMID 40542081, 2025). "NOD2-smoking interaction was most frequently investigated and showed variant-specific effect at rs2066847 regarding the risk of Crohn’s disease." (PMID 40464295, 2025). "Inhibiting or silencing ABHD17 isoforms increases S-acylation and functionality of NOD2 and a subset of Crohn’s disease-associated variants." (PMID 40054525, 2025). "Inhibiting ABHD17 increased the plasma membrane localization of wild-type NOD2 and a subset of poorly acylated Crohn’s disease-associated variants." (PMID 40054525, 2025). "Mutations in ATG16L1, linked to Crohn’s disease, interfere with the interaction between NOD2 and RIPK2, resulting in the suppression of RIPK2 signaling and heightened inflammatory responses." (PMID 40406369, 2025). "Dysregulation of S-acylation in NOD2 is associated with Crohn’s Disease (hypo-acylated) and Blau syndrome/early-onset sarcoidosis (hyper-acylated)." (PMID 40613780, 2025). "In one such study, a combine deficiency of Nod2 and Cybb, known Crohn's disease susceptibility genes, caused the accumulation of the pathobiont, Mucispirillum scheaedleri, that triggered the onset of colitis in a mouse model." (PMID 40671790, 2025). "NOD2, the strongest genetic risk factor for Crohn’s disease, interacts with ATG16L1 and is crucial for antimicrobial autophagy in phagocytes." (PMID 40649913, 2025). "Intestinal epithelial overexpression of the Th17 cell chemoattractant CCL20 is implicated in inflammatory bowel disease and influenced by NOD2 mutations in Crohn’s disease." (PMID 40542081, 2025). "In Crohn’s disease, NOD2 mutations disrupt the negative regulation of the NOD2–NF-κB signaling axis, leading to excessive immune activation." (PMID 40649913, 2025). "In particular, genetic variation in NOD2 accounts for 20% of Crohn disease genetic risk, with three common variants." (PMID 40910070, 2025). "Loss-of-function mutations in nucleotide-binding oligomerization domain 2 (NOD2) constitute the primary risk factors for Crohn’s disease." (PMID 39403381, 2024). "Recently, pathogenic variants in the WFS1/RP1/NOD2 genes have been shown to cause congenital cataract, retinitis pigmentosa, and Crohn’s disease in a five generation British family." (PMID 38984127, 2024). "NOD2 represents the most relevant susceptibility gene for Crohn’s disease, frequently associated with the phenotype that develops strictures, ileal damage, and presents an increased risk of surgical intervention." (PMID 39125988, 2024). "Mutations in the nucleotide binding oligomerization domain containing 2 (NOD2) was identified the first susceptibility gene for increasing the risk of Crohn's disease." (PMID 38451044, 2024). "NOD2 is the first conferred and one of the most important susceptibility genes of Crohn’s disease, which participates in regulating inflammatory response to bacterial antigens." (PMID 39095853, 2024).
Crohn disease (continued). "Mutations and single nucleotide polymorphisms (SNPs) in NOD2 confer genetic susceptibility to a range of autoimmune and autoinflammatory disorders, including Crohn’s disease, Blau syndrome, and Yao syndrome." (PMID 39329913, 2024). "NOD2 variants are associated with Crohn's disease, in which a defect in recognizing commensal bacteria leads to gastrointestinal inflammation." (PMID 39206364, 2024). "Certain NOD2 sequence variants are suspected to result in dysregulation of immune/inflammatory responses, and loss-of-function variants are associated with Crohn’s disease while gain-of-function variants are associated with Blau syndrome." (PMID 39430755, 2024). "The identification of a specific mutation (rs2066845) of NOD2 in first-degree relatives of patients with Crohn’s disease explained the abundance of Erysipelotrichaceae in the feces." (PMID 39125988, 2024). "Mutations in NOD2 associated with Crohn’s disease are predominantly confined to the LRR domain and have been demonstrated to abolish MDP detection and NF-κB activation." (PMID 39329913, 2024). "NOD2 SNPs represent the most potent known genetic risk factor for Crohn’s disease development; however, the precise mechanism by which NOD2 variants contribute to disease pathogenesis remains incompletely understood." (PMID 39329913, 2024). "Together with ATG16L1, another susceptibility locus for Crohn’s disease, NOD2 triggers the process of autophagy by accumulating at the site where bacteria gather." (PMID 39095853, 2024). "NOD2 mutations associated with Crohn’s disease tend to be confined to the LRR domain and have been shown to abrogate MDP detection and activation of NF-κB in transient transfection experiments." (PMID 37869013, 2023). "Map infection was reported in patients with NOD2 polymorphisms and/or Crohn’s disease, but a causative role for Map in Crohn’s disease is elusive." (PMID 37262021, 2023). "The first Crohn’s disease susceptibility gene nucleotide-binding and oligomerization domain 2 (NOD2) represents a cornerstone of this concept." (PMID 36413074, 2023). "NOD2 has been reported to be associated with Crohn’s disease and plays important roles in microbe sensing and host response." (PMID 38124066, 2023). "NOD2 gene polymorphism has been implicated in the etiology of Crohn’s disease through genome-wide association studies (GWAS) and meta-analyses." (PMID 37833958, 2023). "Polymorphisms in the autophagy gene ATG16L1 are also linked to Crohn’s disease like NOD2, suggesting another shared pathway, and the possibility of a contributing bacterial agent vis-à-vis autophagic control of the intruder." (PMID 37262021, 2023). "Three common NOD2 variants (R702W, G908R, and 3020insC) are linked to the development of Crohn’s disease." (PMID 37869013, 2023). "Nucleotide-binding oligomerization domain containing 2 (NOD2) is a gene, associated with Blau syndrome, Crohn’s disease (CD) and most recently with a polygenic autoinflammatory disease with onset in adulthood called NAID or YAO-Syndrome." (PMID 37848930, 2023). "Mutations in NOD2 have been strongly associated with Crohn’s disease, especially the common LRR domain mutations 2104CT (R702W), 2722GC (G908R), and 3020insC (1007FS)." (PMID 37262021, 2023). "Crohn’s disease (CD) is associated with polymorphisms in NOD2 (also known as NLRC2), an innate sensor of bacterial infection for immune response." (PMID 37884500, 2023). "Polymorphisms in NLRC2 (NOD2) are the strongest known genetic risk factors in the development of Crohn’s disease." (PMID 37869013, 2023). "Studies on Crohn’s disease have consistently implicated NOD2 as the most important gene associated with the disease and NOD2 gene mutations have been implicated in disease severity." (PMID 37686309, 2023). "Dysfunctional NOD2 signaling resulting from NOD2/CARD15 mutations can disrupt immune homeostasis in Crohn’s disease." (PMID 37998389, 2023).
Crohn disease (continued). "NOD2 polymorphisms are the strongest risk factor for Crohn’s disease (CD), one of the major types of IBD37." (PMID 37286542, 2023). "Polymorphisms of NOD2 have been associated with Crohn’s disease, an inflammatory bowel disease, and Blau syndrome, an autoinflammatory condition." (PMID 38124066, 2023). "It was also determined that many human NOD2 mutations associated with Crohn’s disease are inefficiently acylated, explaining their loss-of-function phenotype." (PMID 37869013, 2023). "DCs generated by Crohn’s Disease patients with homozygous NOD2 mutations have a reduced capacity to produce IL-23 and induce TH17 when primed with TLR2 ligands in addition to MDP." (PMID 36677464, 2023). "Genetic and genome‐wide association studies have enhanced our understanding of many complex inflammatory diseases (e.g., NOD2 variants in Crohn's disease)." (PMID 36175368, 2023). "Mutations and single nucleotide polymorphisms of NOD2 create a genetic predisposition for autoimmune (Crohn’s disease) and autoinflammatory diseases (Blau syndrome, Yao syndrome, early-onset sarcoidosis, and atopic disorders)." (PMID 37869013, 2023). "Limitation of the study: It is estimated that homozygous or heterozygous NOD2 mutations are prevalent in up to 40% of patients with Crohn’s disease." (PMID 37240707, 2023). "Soon after the discovery that NOD2 makes an unusually large contribution to Crohn’s disease risk in Europeans, potential clinical utility in prediction of fibrostenotic disease progression or need for surgery was considered." (PMID 37968638, 2023). "Mutations in the NOD2 gene are closely related to two distinct granulomatous diseases: Crohn's disease (CD) and Blau syndrome." (PMID 36915122, 2023). "Crohn’s disease (CD) is an inflammatory bowel disease (IBD) with a multifactorial etiology influenced by variants in NOD2." (PMID 35741735, 2022). "This also applies also to NOD2, which profoundly affects the intestinal microbiota in humans; its polymorphisms are related to Crohn’s disease." (PMID 36428390, 2022). "NOD2 protects ISCs against reactive oxygen species toxicity, and mutations in NOD2 are associated with Crohn’s disease and intestinal tumorigenesis." (PMID 35303435, 2022). "Crohn’s disease-associated mutations in NOD2 and ATG16L1 render these proteins inactive for autophagy induction." (PMID 37425656, 2022). "Polymorphisms in the gene encoding NOD2 have been linked to a growing number of chronic inflammatory disorders, such as Crohn’s disease, Blau syndrome, and early-onset sarcoidosis." (PMID 36146565, 2022). "The inability of MDP to activate forms of NOD2 carrying mutations associated with Crohn’s disease has been observed in both in vitro and in vivo studies." (PMID 36146565, 2022). "Whole-exome sequence revealed two rare variants in NOD2, one of which has been associated with susceptibility Crohn's disease." (PMID 35211430, 2022). "As such, this analysis also sheds light on the role of NOD2 risk polymorphisms in the LRR domain occurring in Crohn’s disease." (PMID 36189261, 2022). "More than 30 variants of the NOD2/CARD15 gene have been identified, while an increased risk of Crohn’s disease development was connected to R702W, G908R, and L1007fs variants, as well as P268S and IVS8+158 polymorphisms." (PMID 35634292, 2022). "For example, the PGN receptor NOD2 is enriched in ISCs of mice and protects ISCs from irradiation-induced cytotoxicity, while mutations in NOD2 are linked to Crohn’s disease." (PMID 35303435, 2022). "The majority of Crohn’s disease-associated NOD2 mutant proteins displayed a 70% to 90% reduction in S-palmitoylation levels and a dysregulated intracellular localization of NOD2." (PMID 35159374, 2022). "NOD2 haplotypes have been associated with Crohn disease, and a gain-of-function mutation of NOD2 occurs in patients with Blau syndrome, a rare systemic granulomatous inflammatory disease." (PMID 35205739, 2022).